TNF (tumor necrosis factor)
Diseases named in the same sentence as TNF in open-access papers (continued):
Sharing a sentence is not in itself a finding about the gene and the disease.
vasculitis (continued). "The vasculitis and autoinflammation of DADA2 patients are relieved by treatment with monoclonal antibodies directed against TNF." (PMID 39403923, 2024). "Prescribing anti‐tumor necrosis factor (TNF) agents (etanercept, infliximab, and adalimumab) in patients with vasculitis phenomena, including strokes, seems to be the cornerstone of DADA2 treatment and reduces levels of inflammatory markers." (PMID 39588247, 2024). "Currently, TNF-α inhibitors are the treatment of choice in DADA-2 patients and results effective on controlling the vasculitis signs and preventing the strokes." (PMID 37179309, 2023). "In diseases like Kawasaki disease, blood markers such as tumour necrosis factor α (TNFα), interferon-γ (IFN-γ), interleukins (e.g., IL-6), and monocyte chemoattractant protein (MCP)-1 contribute to the development of the vasculitis process." (PMID 37629654, 2023). "Based on PPI analysis, the overlapped genes with higher degrees in the hub gene network included MAPK1, MAPK3, VEGFA, TNF, and AKT1, implying that they were involved in the process of HXTLF treatment against vasculitis." (PMID 36034958, 2022). "ADA2 deficiency results in a predominance of M1 macrophages characterized by increased production of pro-inflammatory cytokines, such as tumor necrosis factor alpha (TNF alpha), an important mediator of vasculitis and tissue damage." (PMID 35774100, 2022). "In mouse vasculitis and intraretinal inflammatory infiltrates, AQP1 protein expression downregulated TNF-α in mouse retinal pigment epithelium (RPE) cells." (PMID 31529146, 2019). "This study revealed the effects of LA on endothelial cell activation, NLRP3, IL-1β, TNF-α, IL-32, and CCL-2, VCAM-1, MCP-1, and the spleen tyrosine kinase (Syk)--p38/JNK signaling axis and its effect on vasculitis in rats." (PMID 30158835, 2018). "In those with RA in whom the onset/deterioration of vasculitis is suspected, the presence or absence of TNF‐α inhibitor therapy should be investigated." (PMID 40292847, 2025). "The current study noted that serum PDGF-CC levels in KD patients were positively correlated with WBC, N%, IL-2, IL-12p70, TNF-α, and IL-1β and negatively correlated with L%, supporting the hypothesis that PDGF-CC exerts its effect in the KD vasculitis." (PMID 38273388, 2024). "Unlike patients with DADA2 and vasculitis, cases with pure red cell aplasia and bone marrow failure are largely refractory to TNF inhibitors." (PMID 33757531, 2021). "In addition, anti-TNF therapy, which is preferential for DADA2 patients with vasculitis (as for P7), was missed." (PMID 33757531, 2021). "Five-month-old controls that do not overexpress TNF-α (TNF-PAD4+/+) show no inflammatory infiltrates or destructive vasculitis." (PMID 27450561, 2016). "Regarding other vasculitis, published data are not in favor of efficiency of anti-TNF-α which, therefore, should not be used." (PMID 24719524, 2014). "Anti-TNF-α treatments in vasculitis did not demonstrate the same efficacy as in other inflammatory diseases such as RA." (PMID 24719524, 2014). "These molecules have also been tested in other autoimmune and inflammatory systemic diseases such as severe vasculitis refractory to conventional treatment but, to date, vasculitis are not included in the list of therapeutic indications of anti-TNF-α agents." (PMID 24719524, 2014). "Our study suggests that TNF-α has an important role in the pathogenesis of vasculitis in KD, and serum levels of TNF-α could be a biomarker reflecting the severity of vasculitis of KD." (PMID 23606968, 2013). "Type 1 cytokines like TNF-α and IFN-γ can induce apoptosis in trophoblast cells, suppress growth-supporting cytokines from the uterine epithelium, and activate coagulation pathways, potentially leading to vasculitis and impaired maternal blood supply to the embryo." (PMID 40141672, 2025).
vasculitis (continued). "In addition, none of the patients experienced vasculitis recurrence after switching to another agent within the same class or changing to a biologic agent with a non-TNF-related mechanism of action." (PMID 37176606, 2023). "Furthermore, the expression of TNF-α, but not of IL-6, induced immune cell infiltration into the vitreous as well as vasculitis, and subsequently induced the development of fibrosis and epiretinal membranes." (PMID 34520511, 2021). "Although the efficacy of MTX on vasculo-BD has not been established, the combination therapy with anti-TNF-α agents seemed to be effective in other BD-related vasculitis including retinal and entero-vasculitis, suggesting MTX can also be a reasonable immunosuppressive agent for vasculo-BD." (PMID 27034879, 2016). "Furthermore, we found that the degree of vasculitis correlated most significantly with TNF-α levels in each animal in all groups, which suggests that TNF-α plays a dominant role in regulating inflammatory changes regardless of the suppressive agents administered." (PMID 23606968, 2013). "Anecdotal including invasive sphenoidal sinus aspergilloma and fatal cases have been reported in patients with vasculitis, such as Wegener's disease and temporal arteritis, but there are not included in the present review since anti-TNF agents are not indicated in these conditions." (PMID 19886992, 2009). "Use of tumor necrosis factor inhibitors (predominantly infliximab) and the interleukin-6 inhibitor tocilizumab has also been used with success for rheumatologic irAEs, but to our knowledge, they have not been used for CPI-vasculitis." (PMID 35251725, 2022). "Furthermore, the induction of AAV-IL-10 prevented the expression of TNF-α and IL-6, but not GM-CSF and Dectin-2 at the early phase of CAWS-induced vasculitis." (PMID 29765083, 2018).
Chagas disease (126 papers, 2010 to 2025). A parasitic infection caused by Trypanosoma cruzi. "It has been observed in patients during the chronic phase of Chagas disease that high levels of TNF are associated with poor cardiac function." (PMID 38543309, 2024). "Pathways such as TNF signaling, Yersinia infection, insulin resistance, proximal tubule bicarbonate reclamation, osteoclast differentiation, Chagas disease, and the sphingolipid signaling pathway were associated with the decreased DE genes." (PMID 39524487, 2024). "Nitric oxide locally produced through the iNOS signaling pathway has been implicated in thymic atrophy during infection by Mycobacterium avium, and TNF-α has also been associated with thymic atrophy in Chagas disease, caused by the parasite Trypanosoma cruzi." (PMID 32823553, 2020). "TNF‐α has been widely implicated in the pathogenesis of Chagas disease 28 and used as an indicator of T cell function when detected intracellularly or in sera." (PMID 28967229, 2018). "Aiming to investigate the influence of the TNF polymorphisms on Chagas disease, TNFA (positions −308 rs1800629, −244 rs673, −238 rs361525, and −1031 rs1799964) and TNFB genotypes have been interrogated." (PMID 24069594, 2013). "Higher levels of IFNγ and TNFα are associated with lower levels of IL-4 and IL-10, in both cardiac and more severe forms of Chagas disease, and high levels of IL-10 or moderate levels of IFNγ are associated with the indeterminate form." (PMID 24216069, 2013). "Lastly, as TNFα production has been associated with cardiac damage in Chagas disease, it will be of interest to test the production of TNFα on T. cruzi specific DP T cells." (PMID 21886854, 2011). "Moreover, the treatment of mice with rlL9 was linked with decreased levels of IL-12, IL-6, and TNF-α levels in Chagas disease." (PMID 36293524, 2022). "The depletion of the T-cell population, especially the double-positive lymphocytes in the thymus, was reported in Chagas disease, a pathology associated with regression of the thymus and intrathymic and systemic contents of TNF-α during the acute T. cruzi infection." (PMID 35276973, 2022). "Several studies have shown the important role of cytokine-mediated immunoregulation in the maintenance of asymptomatic clinical forms during the progression of Chagas disease, mainly associated with the production of modulatory cytokines IL-10 and pro-inflammatory cytokines TNF-α and IFN-γ." (PMID 30662439, 2018). "Transforming growth factor β1 (TGF-β1) and tumour necrosis factor (TNF) have been implicated in Chagas disease pathophysiology and may correlate with left ventricular (LV) function." (PMID 29513876, 2018). "In Chagas disease patients, high TNF plasma levels are associated with disease severity." (PMID 28877735, 2017). "Furthermore, kinetic investigations on the activation of macrophages during Chagas disease, demonstrated that macrophages of mice susceptible to infection produce higher levels of TNF-α than macrophages from resistant mice strains." (PMID 22412949, 2012). "In this respect, the delicate balance between the ability of TNF-alpha to control parasite growth and to promote tissue damage may be responsible for human resistance/susceptibility to Chagas disease." (PMID 21408088, 2011). "Severe and end-stage Chagas disease has been associated with high levels of TNF-alpha." (PMID 21408088, 2011). "IFN-γ and TNF-α signaling, which are constitutively upregulated in Chagas disease patients, negatively affect mitochondrial function and adenosine 5′-triphosphate (ATP) production–cytokine-induced mitochondrial dysfunction." (PMID 40297326, 2025). "The roles of the TNF signaling pathway, Chagas disease, and the Estrogen signaling pathway were also frequently reported in anti-OP activities." (PMID 35888070, 2022). "In the chronic phase of Chagas disease, elevated levels of TNF and IFN-γ are described in chagasic patients, as a probable response to the persistence of the parasite due to the immune response." (PMID 35928208, 2022).
Chagas disease (continued). "In terms of KEGG enrichment, these genes were enhanced in the TNF signaling pathway, NF−kappa B signaling pathway, and Chagas disease." (PMID 35647198, 2022). "CD8+ T lymphocytes mediate protection against infection by secreting cytokines such as IFN-γ and TNF; however, chronic stimulation is involved in the inflammatory process of Chagas’ disease." (PMID 34722343, 2021). "The top five enriched KEGG categories were the cytokine–cytokine receptor interaction, PI3K-Akt signaling pathway, Chagas disease (American trypanosomiasis), TNF signaling pathway, and osteoclast differentiation." (PMID 33810608, 2021). "The most significant pathways of common targets are the AGE–RAGE signaling pathway in diabetic complications, Chagas disease (American trypanosomiasis), and the TNF signaling pathway." (PMID 33681222, 2021). "We confirmed four significantly enriched pathways common to both the M1 and M5 modules, which were the pathways for cAMP signaling, cocaine addiction, Chagas disease, and TNF signaling." (PMID 33086708, 2020). "Our findings in the present study show that Parp1 deletion was beneficial in controlling the myocardial inflammatory infiltrate, especially the TNF-α-expressing Mφ, in Chagas disease." (PMID 32315358, 2020). "This is the first study to explore the correlation between TGF-β1 and TNF serum levels and both LV systolic and diastolic functions in patients with Chagas disease." (PMID 29513876, 2018). "While TNF were increased in patients with Chagas disease HF, TGF-β1 serum levels were decreased in patients with stages B, C, and D of the cardiac form." (PMID 29513876, 2018). "This intracellular protozoan parasite is the etiologic agent of Chagas disease, a neglected tropical disease characterized by a systemic inflammatory response enriched in TNF in chronic patients and experimental models." (PMID 28877735, 2017). "The strong positive correlation between PPAR-α and NF-κB only in the previously exercised animals suggests that PPAR-α interacts with TNF-α and NF-κB, which is involved in the development of apoptosis, similar to what occurs in Chagas' disease." (PMID 27074178, 2016). "During severe cardiomyopathy of the chronic phase of Chagas disease, the occurrence of intense inflammatory response is correlated with the production of type 1 cytokines, such as TNF-α and IFN-γ." (PMID 26090399, 2015). "Patients with the acute phase of Chagas disease display increased circulating levels of IL-6 and TNF-α and increased production of IFN-γ by mononuclear cells." (PMID 25210230, 2014). "In the chronic phase of Chagas disease, TNF-α seems to be closely related to cardiac dysfunction owing to its negative inotropic effect, in both experimental models and humans." (PMID 25050370, 2014). "The expressions of different cytokines (IL-10, IFN-γ, TNF-α, IL-6, IL-1β) were evaluated in the plasma of healthy individuals and patients with different forms of Chagas disease." (PMID 24603474, 2014). "Not only the level of this cytokine, but the cells involved in its production and the elapsed time after interaction with the parasite should be investigated to improve the current understanding of the role of TNF-alpha in Chagas disease." (PMID 21408088, 2011). "Further analysis revealed that about 10 KEGG pathways were involved in the host immune response to bacterial challenge; these included the TNF signaling pathway, IL-17 signaling pathway, antigen processing and presentation pathway, Chagas disease pathway, and TLR signaling pathway, among others." (PMID 35844551, 2022). "In the present study, the main immune-related signaling pathways in the intestine of P. shigelloides-infected C. carpio were the TNF signaling pathway, IL-17 signaling pathway, antigen processing and presentation pathway, Chagas disease pathway, and TLR signaling pathway." (PMID 35844551, 2022).
Chagas disease (continued). "In terms of the KEGG enrichment analysis, the pathways in cancer (hsa05200), Influenza A (hsa05164), the TNF signaling pathway (hsa04668), Chagas disease (American trypanosomiasis) (hsa05142), the Estrogen signaling pathway (hsa04915), etc., were the vital signaling pathways linked to anti-OP." (PMID 35888070, 2022). "The immune-related signaling pathways of all enriched immune-related DEGs were selected as the top 10 ones, e.g., the TNF signaling pathway, IL-17 signaling pathway, antigen processing and presentation pathway, Chagas disease pathway, and Toll-like receptor (TLR) signaling pathway." (PMID 35844551, 2022). "In the transwell migration assays, the combination of fibronectin with TNF-α induced an increase in the migratory response of lymphocytes from patients with Chagas disease, revealing the functional relationship between cytokines and ECM proteins such as fibronectin." (PMID 34796122, 2021). "Previous studies found elevated TNF serum levels only in patients with Chagas disease HF, while others detected elevated TNF serum levels elevated in both indeterminate and Chagas disease HF patients." (PMID 29513876, 2018). "TNF showed a positive correlation with LV end-diastolic diameter and negative correlation with LV ejection fraction in patients with Chagas disease, while others studies found this same correlation only in patients with the cardiac form of Chagas disease." (PMID 29513876, 2018). "Tumour necrosis factor (TNF) is a proinflammatory cytokine with increased expression in HF and may play a key role in the immunological imbalance governing Chagas disease progression to the cardiac form." (PMID 29513876, 2018). "Recent studies have investigated the role of TNF-alpha gene polymorphisms in Chagas disease, but none of those studies evaluated a population from an endemic area or used the clinical assessment criteria established here." (PMID 21408088, 2011). "TNFα levels were higher in group 1 as comparedto group 0 and a significant trend towards increasing levels was observed accordingworsening clinical forms of Chagas disease." (PMID 20877635, 2010). "In contrast to TNF-dependent modulations, our own data point to IL-4 as a soluble factor in T. cruzi-infected mice that may contribute to stromal cell alterations during the acute phase of Chagas disease." (PMID 30619242, 2018). "However, the effect of TNF in the CNS during Trypanosoma cruzi infection is unclear." (PMID 28877735, 2017). "During Trypanosoma cruzi infection, the immune system activates a robust inflammatory response, involving cytokines and chemokines like IFN-γ, TNF, IL-6, IL-1β, CCL2, and CCL5, to control parasite replication." (PMID 40936920, 2025). "Specifically, transforming growth factor β (TGF-β), tumor necrosis factor-α (TNF-α) and interferon gamma (IFN-γ) have also been proven to be key players in the immune response and pathogeny of Chagas disease." (PMID 39000409, 2024). "Chagas disease affects 8 million people worldwide, and chronic production of the cytokines IFN-γ and TNF-α by T cells together with mitochondrial dysfunction are important players for the poor prognosis of the disease." (PMID 34867992, 2021). "The five signal pathways are follows: TNF signaling pathway, pathways in cancer, calcium signaling pathway, HIF-1 signaling pathway, and Chagas disease (American trypanosomiasis), respectively." (PMID 33628326, 2021). "The pathways involved include TNF signaling pathway, pathways in cancer, HIF-1 signaling pathway, Chagas disease (American trypanosomiasis), and calcium signaling pathway." (PMID 34725557, 2021). "Peptides from each protein were recognized by PBMC from chronic Chagas disease patients and peptide-specific CD8+ T cells exhibited a pro-inflammatory cytokine secretion profile (IFN-γ, TNF-α and IL-6)." (PMID 34267750, 2021).